DPP4 (dipeptidyl peptidase 4)
Diseases named in the same sentence as DPP4 in open-access papers (continued):
Sharing a sentence is not in itself a finding about the gene and the disease.
Hypoglycemia (continued). "DPP-4 inhibitors have advantages such as lack of hypoglycaemia and weight gain which justifies combining DPP-4 inhibitors with insulin." (PMID 37287751, 2023). "Another study has demonstrated that the use of incretin enhancers (DPP-4 inhibitors) and mimetics (GLP-1 agonists) alone, without combination with sulfonylurea, has a low risk of resulting in hypoglycemia." (PMID 38169925, 2023). "In an RCT and a nationwide cohort study, the results showed no increased risk of hypoglycaemia with SGLT-2i monotherapy; however, SGLT-2i were associated with approximately twice the risk of diabetic ketoacidosis as DPP4 inhibitors." (PMID 33888126, 2021). "Furthermore, dipeptidyl peptidase 4 (DPP4) inhibitors combined with metformin therapy improved glucose level with a significantly greater reduction in GV and hypoglycemia." (PMID 33413392, 2021). "The odds ratio of the hypoglycemic incidence rate was 1.02 (95% CI: 0.74 to 1.42, 4596 patients from 11 studies), indicating that adding a DPP-4 inhibitor did not significantly increase the incidence of hypoglycemia." (PMID 33224988, 2020). "All existing meta-analyses were consistent in their conclusions that DPP-4 inhibitors significantly reduced HbA1c levels without increasing hypoglycemia." (PMID 33224988, 2020). "The addition of DPP-4 inhibitors to insulin therapy for adult patients with type 2 DM can significantly reduce HbA1c levels without increasing the occurrence of hypoglycemia." (PMID 33224988, 2020). "Dipeptidyl peptidase-4 (DPP-4) inhibitors could effectively reduce HbA1C and postprandial hyperglycemia and could incur only minimal danger of hypoglycemia." (PMID 30611254, 2019). "For medications used in the hypoglycemia group, 6 of the 7 patients used DPP-4 inhibitors, and half of these 6 patients also used insulin secretion stimulators [e.g., sulfonylureas (SU) and glinide] in combination with DPP-4 inhibitors." (PMID 30815039, 2019). "As might be expected from previous comparative analysis, there was an improvement in weight change and reduction in rates of hypoglycaemia where there was a rapid increase in the use of SGLT2 inhibitors and DPP‐4 inhibitors in place of sulphonylureas." (PMID 30828962, 2019). "The studies had similar outcomes: DPP-4 inhibition and sulfonylurea both reduced HbA1c, DPP-4 inhibition had no weight gain, which on the contrary was seen with sulfonylurea, and there was a marked difference in hypoglycemia episodes." (PMID 31275243, 2019). "DPP-4 inhibitors significantly increased the GLP-1 and GIP levels, reduced the glucagon levels during hyperglycemia, and sustained glucagon counterregulation during hypoglycemia in patients with T1DM." (PMID 29507862, 2018). "Currently, two pharmacologic classes, DPP4 inhibitors and SGLT2 inhibitors, show promise as preferred second-line treatment options given their weight neutral and weight lowering effects, respectively, and low potential for hypoglycemia." (PMID 30304106, 2018). "Our study showed as follows; accompanied with insulin, switching from DPP-4 inhibitors to dapagliflozin maintained an equivalent glucose fluctuation and all-day and nocturnal hypoglycaemia prevalence without significant insulin dosage change." (PMID 28725273, 2017). "This is consistent with earlier findings that DPP-4 inhibitors do not increase hypoglycemia rates, even though they increase insulin secretion in a glucose-dependent manner." (PMID 29037205, 2017). "Since 2008, two other very promising therapeutic classes have been placed on the market: dipeptidyl peptidase-4 (DPP-4) inhibitors and glucagon like peptide 1 (GLP-1) analogues to promote insulin secretion without the risk of hypoglycemia." (PMID 28105440, 2016). "As previously reported in meta-analyses, the rate of hypoglycemia was not higher in T2DM patients treated with the DPP-4 inhibitors, even in patients already undergoing treatment with insulin or a sulfonylurea." (PMID 26500706, 2015).
Hypoglycemia (continued). "Compared with placebo or no treatment, DPP-4 inhibitor therapy did not increase the incidence of hypoglycemia (1,049 participants, random RR 1.10, 95%CI 0.92 to 1.32; p = 0.30), and there was no heterogeneity (I2 = 0%; p = 0.43)." (PMID 25360775, 2014). "Sitagliptin, a dipeptidyl-peptidase-4 (DPP-4) inhibitor, has a low incidence of hypoglycemia, is weight neutral, and, in a small study, did not affect immunosuppressant levels." (PMID 24817885, 2014). "In contrast, the odds of hypoglycaemia for dapagliflozin and DPP-4 inhibitors were not significantly different to placebo (p > 0.05)." (PMID 25006351, 2014). "Regarding safety, data revealed that there was no change in the incidence of hypoglycemia with DPP-4 inhibitor treatment." (PMID 25360775, 2014). "If the insulin dose is minimal, it may be possible to discontinue insulin and switch to medications such as alpha-glucosidase inhibitors, dipeptidyl peptidase-4 (DPP-4) inhibitors, and glucagon-like peptide-1 receptor agonist (GLP-1RA)to manage blood sugar levels while also preventing hypoglycemia." (PMID 39575003, 2024). "Combining a DPP-4 inhibitor with insulin therapy may be useful in patients with T2DM for improving glucose control without prompting hypoglycaemia and likely suitable for restricting weight gain." (PMID 37287751, 2023). "On the contrary, reducing glucagon can be achieved safely through incretin mimetics drugs: both dipeptidyl peptidase 4 inhibitors (DPP-4i) and glucagon like peptide 1 analogues (GLP-1a) proved to reduce glucagon levels in a glucose dependent manner, preserving glucagon response to hypoglycemia." (PMID 35563608, 2022). "DPP4 inhibitors, such as sitagliptin, vildagliptin, and linagliptin, can increase the secretion of incretin and GLP-1, thereby improving glycemic control without causing hypoglycemia and weight gains." (PMID 34493714, 2021). "If glycemic target values are not reached, DPP-4 inhibitor may be replaced by a GLP-1 receptor agonist, with the advantages of higher HbA1c-lowering effect, without increasing the risk of hypoglycemia, and with the potential ability to reduce BW." (PMID 31313243, 2020). "Diverse drugs were being used by patients of the hypoglycemia subgroup (DPP-4 inhibitor by 1 patient, biguanide alone by 1, multiple oral glucose-lowering drugs by 1, and insulin mixture by 1 patient), but none developed severe hypoglycemia." (PMID 30815039, 2019). "DPP-4 inhibitors act by increasing active glucagon-like peptide-1 (GLP-1) in blood through inhibition of DPP-4, which stimulates glucose-dependent insulin secretion and inhibits glucagon secretion, leading to reduced glucose levels with a low incidence of hypoglycemia." (PMID 29435909, 2018). "The infrequency of insulin-providing agents and DPP-4 inhibitors in the good GC subgroup than in others may contribute to the tight GC without hypoglycemia." (PMID 29545773, 2018). "Dipeptidyl peptidase-4 (DPP-4) inhibitors, a popular class of anti-diabetic medications, have been shown to achieve improved glycemic control by lowering HbA1C, without causing hypoglycemia, and are weight neutral." (PMID 29724198, 2018). "DPP-4 inhibitors also prevent the degradation of insulin secretagogues such as glucagon-like peptide-1 (GLP-1), thereby ameliorating hyperglycaemia without causing hypoglycaemia." (PMID 26767505, 2016). "However, because DPP-4 inhibitor monotherapy does not induce hypoglycemia, the M-value may merely serve as an index of hyperglycemia, similar to the HbA1c." (PMID 38256615, 2024). "Moreover, hypoglycemia is a frequent side effect of therapeutic treatment with insulin, sulfonylureas or glinides, while other treatments (metformin, acarbose, thiazolidinediones, GLP-1 receptor agonists, and DPP-4 inhibitors) are capable of reducing hyperglycemia without inducing hypoglycemia." (PMID 31366085, 2019).
Hypoglycemia (continued). "On the other hand, we recently reported that treatment with sitagliptin, a dipeptidyl peptidase-4 (DPP-4) inhibitor, attenuated the progression of carotid IMT in insulin-treated patients with T2DM compared with the conventional treatment without increasing the risk of hypoglycemia." (PMID 28250768, 2017). "The incidence of hypoglycemia, which is an important component of safety, increased significantly with addition of sulfonylureas, glinides, or insulin, but did not increase significantly with alfa-glucosidase, DPP4 or SGLT2 inhibitors, GLP1 agonists, or thiazolidinediones 39-41." (PMID 27546934, 2016). "Dipeptidyl peptidase 4 (DPP-4) inhibitors increase insulin secretion and suppress glucagon secretion in a glucose-dependent manner through enhancement of the effect of endogenous incretin, thereby improving postprandial glycemic excursion without increasing the risk of hypoglycemia." (PMID 25314300, 2014). "Compared whether the oral combination of an SGLT2 inhibitor (DAPA) and a DPP4 inhibitor (SAXA) could achieve similar glycemic control to basal insulin in T2DM patients poorly controlled with metformin, without causing an increase in hypoglycemia or body weight." (PMID 39618646, 2024). "Dipeptidyl peptidase 4 (DPP4) inhibitors like sitagliptin are widely used and tolerated in the management of T2DM with minimal or no hypoglycemia as an adverse effect." (PMID 37173803, 2023). "DPP-4 inhibitors, commonly known as gliptins, prevent DPP-4 activity to inhibit the rapid breakdown of endogenously generated GLP-1, consequently promoting glucose regulation without generating hypoglycemia." (PMID 37893048, 2023). "Therefore, DPP-4 inhibitors increase the concentrations of GLP-1 and GIP, which act in pancreatic β-cells by releasing insulin, and in pancreatic α-cells, inhibiting the secretion of glucagon in a glucose-dependent manner, thus controlling blood glucose with no risk of hypoglycemia." (PMID 27471550, 2016). "In fact, pioglitazone, DPP-4 inhibitors, GLP-1 agonists and acarbose, unlike insulin, could all have some beneficial effect on cardiovascular risk; furthermore, they do not induce hypoglycemia, which is negative cardiovascular mortality and they require no regular blood glucose self-monitoring." (PMID 24348585, 2013). "Combining DPP-4 inhibitors with metformin resulted in greater reductions in HbA1c (MD = −0.49) and FPG (MD = −0.80) but did not further reduce cardiovascular events (RR = 0.54), hypoglycemia (RR = 1.04), or gastrointestinal side effects (RR = 0.98)." (PMID 40574081, 2025). "Our results also show that two dipeptidyl peptidase-4 inhibitors (DPP4) considered as second-line treatments were used more frequently, in combination with metformin, probably to induce a greater weight reduction without intense hypoglycemia." (PMID 32722515, 2020).
Obesity (253 papers, 2010 to 2026). Accumulation of substantial excess body fat. "Semaglutide, the next FDA-approved GLP-1RA medication, demonstrates greater weight loss in patients with obesity, mediated by its increased half-life compared to liraglutide through modification to inhibit degradation by dipeptidyl-peptidase-4 (DPP-4)." (PMID 40722684, 2025). "Suppression of pathological activation of HIF1α signaling has been shown to increase the relative frequencies of adipogenic gWAT APCs and iWAT DPP4 + APCs, which is associated with enhanced protective adipocyte hyperplasia in obesity." (PMID 38509584, 2024). "Plasma DPP4 levels are elevated in several settings associated with metabolic dysfunction, such as obesity; chronic liver disease, including NAFLD and hepatitis C infection (HCV); as well as type 1 diabetes and T2D." (PMID 36472923, 2023). "Subsequently, DPP4 was implicated in alleviating metabolism-related diseases such as obesity, chronic liver disease, and atherosclerosis." (PMID 37097759, 2023). "Fat cell volume, BMI, waist circumference, and triglycerides and leptin concentrations, all markers of obesity, are associated with plasma DPP4 concentrations." (PMID 35885620, 2022). "It was also shown that the expression of DPP4 in adipocytes of different WAT depots positively correlates with obesity potentially linked to paracrine functions of DPP4 in its soluble form as adipokine." (PMID 36168895, 2022). "DPP4 has been identified as a potential regulator that links enhanced cancer risk with metabolic diseases such as hyperglycemia and obesity." (PMID 34926239, 2021). "Obesity and insulin resistance are closely associated with increased DPP4 gene expression and soluble DPP4 release." (PMID 34956089, 2021). "Hormone-based therapies including GLP-1 and GIP agonists and dipeptidyl peptidase-4 (DPP-4) inhibitors have been linked to reduced obesity." (PMID 34094026, 2021). "Higher plasma DPP4 (Dipeptidyl Peptidase 4) can be found among patients with obesity, metabolic syndrome, and DM, who are at risk of a severe course of COVID-19." (PMID 33233425, 2020). "Increased DPP4 expression and activity have demonstrated an association with inflammation observed in obesity and metabolic disorders." (PMID 33117158, 2020). "In contrast, multiple studies demonstrated elevated levels of DPP4 activity and sDPP4 in subjects with obesity and/or T2D11,15,39, associated in some analyses with increased sDPP4 expression in circulating T cells." (PMID 32724076, 2020). "Liver-specific DPP4 transgenic mice presented not only elevated systemic DPP4 activity but also a NAFLD-associated syndrome including obesity, hypercholesterolemia, hepatic steatosis, and liver damage." (PMID 31338065, 2019). "Weight gain is also associated with greater Dpp4 expression in the liver of mice prone to diet-induced obesity, independently of the degree of intra-hepatic fat accumulation." (PMID 30828317, 2019). "DPP4 expression is increased during adipose tissue differentiation with increased rate of secretion from adipose tissue in obesity and associated with body mass index (BMI)." (PMID 31402899, 2019). "In mice, hepatocyte Dpp4 expression increases with obesity, and selective elimination of Dpp4 in the liver is associated with reduced levels of soluble DPP-4 in the plasma." (PMID 30828317, 2019). "DPP-4 gene-deficient mice show improved postprandial glucose control and are resistant to the progression of obesity and hyperinsulinemia." (PMID 29270177, 2017). "We have demonstrated that linagliptin, a DPP-4 inhibitor, improves DD in WD-fed female mice, a clinically relevant model of obesity-associated CVD." (PMID 28476142, 2017). "Adipose tissue release of DPP4 was shown to strongly associate with visceral fat and clinical characteristics of dysmetabolic obesity, and DPP4 inhibitors seem to prevent and/or improve liver steatosis." (PMID 28360082, 2017).
Obesity (continued). "There are a number of potential detrimental effects associated with the DPP4 inhibition, along with the inferior clinical efficacy of DPP4 inhibitors in reducing HbA1c and obesity compared with GLP-1 analogs/GLP-1R agonists." (PMID 28194113, 2017). "In the visceral adipose tissue (VAT), the DPP4 tagging SNPs was associated with methylation of DPP4 and affected mRNA abundance, and, in severe obesity, was a risk factor for cardiovascular disease." (PMID 27111895, 2016). "Previous investigators have demonstrated that activation of dipeptidyl peptidase-4, retinopathy, albuminuria, obesity and hypertriglyceridemia are associated with subclinical LV myocardial dysfunction." (PMID 25946999, 2015). "Collectively, there is clear evidence that DPP4 expression and release by adipose tissue play a key role in obesity and T2DM-associated processes, such as inflammation, adipocyte hypertrophy, and IR." (PMID 26284071, 2015). "The DPP4 tagging SNPs were significantly associated with DPP4 methylation, affected mRNA abundance in visceral adipose tissue, and were a cardiovascular risk factor in patients with severe obesity." (PMID 26339796, 2015). "Serum DPP4 is increased in obesity and reduced after weight loss and is a potential biomarker of metabolic syndrome." (PMID 24447654, 2014). "The actual study also revealed an association between the DPP4 %Meth with plasma total-cholesterol levels in severe obesity, which suggests a link between the DPP4 gene and plasma lipid metabolism." (PMID 23379505, 2013). "Furthermore, many studies demonstrated that DPP-4 gene-deficient mice exhibited enhanced postprandial glucose control and resistance to developing hyperinsulinemia and obesity." (PMID 40566497, 2025). "The concentration of circulating DPP-4 is associated with both visceral adipose tissue volume and adipocyte size, and increases concomitantly with the obesity progression, the development of insulin resistance, and the worsening of glucose metabolic abnormalities." (PMID 38476668, 2024). "Several effects have been associated with DPP-4, including degradation of various substrates (such as incretins, neuropeptides, and cytokines) and involvement with inflammatory processes (including cancer, obesity, and T2DM, 20, 37)." (PMID 39054499, 2024). "FAP2 cells demonstrated enhanced expression of the genes encoding DPP4 (Dpp4), an adipose stem cell marker that also identifies Cxcl14-negative FAPs, and endosialin (Cd248), an obesity-associated glycoprotein." (PMID 38954467, 2024). "One study demonstrated that the inflammatory pathways associated with obesity are regulated by liver-derived DPP4, so targeting DPP4 expression could be sufficient to prevent WAT inflammation and insulin resistance." (PMID 38068912, 2023). "DPP4 release strongly correlates with adipocyte size and is considered risk factor for obesity." (PMID 35945358, 2022). "In obesity, DPP4 serum concentration was associated with increased macrophage infiltration of vWAT, high serum levels of leptin, and reduced adiponectin levels, as well as increased circulating levels of inflammatory cytokines, particularly IL-6, IL-12, and TNF-α." (PMID 36499312, 2022). "Additionally, diet-induced obesity in mice was associated with increased expression and release of hepatic DPP4, with early insulin resistance and development of hepatic steatosis." (PMID 35190847, 2022). "Since obesity is also frequently associated with poorer outcomes in COVID-19 patients, DPP-4 inhibition may bring some advantages." (PMID 36289885, 2022). "We have previously utilized ZO rats to elucidate the cellular and molecular mechanisms underlying reversal of obesity-associated DD by several therapeutics, including a beta blocker, a Dipeptidyl peptidase-4 (DPP-4) inhibitor, and a mineralocorticoid receptor blocker." (PMID 33882908, 2021).